Y_RNA (Y RNA )
Gene: Miscellaneous RNA gene on chromosome 21 (36,986,739 to 36,986,851, reverse strand). Ensembl gene ENSG00000207416.
Homologues: Orthologues: chimpanzee Y_RNA (100% identical), macaque Y_RNA (88% identical). Paralogues in human: RNY1 (86% identical), Y_RNA (84% identical), Y_RNA (83% identical), Y_RNA (82% identical), Y_RNA (81% identical), RNY1P11 (80% identical), RNY1P5 (80% identical), RNY1P8 (80% identical), Y_RNA (80% identical), Y_RNA (79% identical), RNY1P13 (78% identical), RNY1P7 (78% identical), and 92 more.